MRPS21 (mitochondrial ribosomal protein S21)
Synonyms: MRP-S21; RPMS21; MDS016; bS21m
Tractability: Small molecule: a structure with a bound ligand is known. PROTAC: ubiquitination databases record sites on it; its protein half-life has been measured.
Gene: Protein-coding gene on chromosome 1 (150,293,854 to 150,308,981, forward strand). Ensembl gene ENSG00000266472.
Subcellular location: Mitochondrion
Subcellular location (Human Protein Atlas): Mitochondria
Pathways (Reactome):
Metabolism of proteins: Mitochondrial ribosome-associated quality control; Mitochondrial translation elongation; Mitochondrial translation initiation; Mitochondrial translation termination
Gene Ontology:
Molecular function: RNA binding; structural constituent of ribosome
Biological process: mitochondrial translation; translation
Cellular component: mitochondrial small ribosomal subunit; mitochondrion; mitochondrial inner membrane; ribosome
Genetic constraint (gnomAD): Loss-of-function variants: 5 observed, 6.27 expected, observed/expected ratio (o/e) 0.8, 90% interval 0.41 to 1.61. That is too few expected variants to judge how well the gene tolerates losing a copy. Missense variants: 74 observed, 86.71 expected, observed/expected ratio (o/e) 0.85, 90% interval 0.71 to 1.04. Synonymous variants: 27 observed, 28.28 expected, observed/expected ratio (o/e) 0.95, 90% interval 0.7 to 1.32.
Homologues: Orthologues: chimpanzee MRPS21 (99% identical), macaque MRPS21 (94% identical), dog MRPS21 (93% identical), guinea pig MRPS21 (92% identical), rat Mrps21 (91% identical), mouse Mrps21 (90% identical), tropical clawed frog mrps21 (70% identical).
Diseases named in the same sentence as MRPS21 in open-access papers:
MRPS21 is named in the same sentence as 8 diseases in open-access papers, as found by Europe PMC text mining. Sharing a sentence is not in itself a finding about the gene and the disease. The quoted sentences say what the papers report.
breast carcinoma (1 paper, 2021). "ABCC5 is described as differentially spliced in SF3B1 mutated breast cancer, and MRPS21 is described as a gene, whose upregulation is associated with poor response to azacytidine in MDS and related cancers." (PMID 34499147, 2021).
hyperopia (1 paper, 2017). A refractive error in which rays of light entering the eye parallel to the optic axis are brought to a focus behind the retina, as a result of the eyeball being too short from front to back. "It must be noted, however, that two of the mitochondrial ribosomal genes (MRPS21 and MRPL2) were also up-regulated in late hyperopia." (PMID 28852117, 2017).
migraine (1 paper, 2024). "Furthermore, in 2024, the Hautakangas team conducted a meta-analysis of three GWAS studies on migraine, confirming multiple risk loci, including TNF-α, MRPS21, and SELENBP1, which are closely linked to inflammatory responses, mitochondrial function, and oxidative stress." (PMID 39850553, 2024). "Although our review did not specifically identify MRPS21 and SELENBP1, functional clustering analysis in our study revealed a close association between migraine and mitochondrial dysfunction and oxidative stress, with corresponding support from transcriptomic, proteomic, and metabolomic data." (PMID 39850553, 2024).
sarcopenia (1 paper, 2022). Progressive decline in muscle mass due to aging which results in decreased functional capacity of muscles. "Mitochondria-related gene MRPS21 has been identified here as well, whose declined expression has been found in sarcopenia or age-related skeletal muscle deterioration." (PMID 35328027, 2022).
MRPS21 also shares sentences with these, for which no sentence is quoted: cancer (1 paper); cholelithiasis (1); COVID-19 (1); heart failure (1).